ALK (ALK receptor tyrosine kinase)
Diseases named in the same sentence as ALK in open-access papers (continued):
Sharing a sentence is not in itself a finding about the gene and the disease.
lung adenocarcinoma (continued). "So far, the efficacy of radiomics in predicting the ALK gene in lung adenocarcinoma is still unknown." (PMID 32266148, 2020). "Information from the PrognoScan database indicated that higher expression of ALK is significantly correlated with lower patient survival in lung adenocarcinoma, suggesting that if we could decrease ALK expression, patient survival rate might be improved." (PMID 33255340, 2020). "Targeted drugs have been developed in lung adenocarcinoma (LADC) for patients with driven gene positive patients such as epithelial growth factor receptor (EGFR) mutation and anaplastic lymphoma kinase (ALK) or ROS proto-oncogene 1(ROS1) rearrangements to inhibit tumor progression." (PMID 32380883, 2020). "Other oncogenic driver mutations or associations between EGFR mutation/ALK rearrangement status and clinicopathological characteristics of patients with lung adenocarcinoma were not evaluated." (PMID 30744664, 2019). "The results also imply that EV-RNAs may serve as a novel circulating biomarker for monitoring treatment response and progress of ALK-translocated lung adenocarcinoma." (PMID 30658414, 2019). "In both studies, we found that ALK-rearranged tumors were more commonly associated with ipsilateral mediastinal or subcarinal lymph node metastasis (N2) compared to ALK wildtype and EGFR mutated lung adenocarcinoma." (PMID 31386689, 2019). "Serum EV-miR-21-5p, miR-486-3p, MEG3 and XIST levels may correlate with disease progression and treatment response in patients with ALK-translocated lung adenocarcinoma prescribed ALK-TKI treatment." (PMID 30658414, 2019). "The patient did not harbor any activating mutation of EGFR, KRAS, or ALK genes; he was diagnosed as poorly differentiated lung adenocarcinoma stage 2B at the age of 51 and was a light smoker that used one pack per year." (PMID 31083279, 2019). "Interestingly, in the present study, 11/16 (69%) cases harbored ALK rearrangements in an unselected rare ovarian metastasis from a lung adenocarcinoma as the most frequent molecular alteration." (PMID 31455365, 2019). "One patient did not exhibit an EGFR mutation or ALK rearrangement in the metastatic tumor, but the primary lung adenocarcinoma did carry an EGFR mutation." (PMID 31455365, 2019). "We have established ALK-translocated lung adenocarcinoma cell lines and subclones." (PMID 30658414, 2019). "Patients with wild type of EGFR and ALK-positive lung adenocarcinoma may represent a potential selective group, which has a better chance of good response to immunotherapy." (PMID 31561631, 2019). "In adenocarcinoma, PD-L1 expression using 22C3 assay at clinically relevant cutoff could be predicted in higher N stage, histologically solid pattern, wild-type EGFR, and ALK positive in lung adenocarcinoma." (PMID 31561631, 2019). "In conclusion, PD-L1 expression using a 22C3 assay at clinically relevant cutoff could be predicted in higher N stage, histological solid pattern, wild-type EGFR, and ALK positive in lung adenocarcinoma." (PMID 31561631, 2019). "One patient did not detected EGFR or ALK mutation in the metastatic tumor, but the primary lung adenocarcinoma did harbor an EGFR mutation." (PMID 31455365, 2019). "The echinoderm microtubule-associated protein-like 4 (EML4)-anaplastic lymphoma kinase (ALK) fusion gene was identified for the first time in 2007 in a 62 year-old male patient with lung adenocarcinoma, ALK-rearrangements serve as a key oncogenic driver that occur in 3%–7% of patients with NSCLC." (PMID 29632648, 2018). "The tumor specimen was also examined as an advanced primary lung adenocarcinoma and assessed for the following tumor markers: epidermal growth factor receptor (EGFR) mutation, anaplastic lymphoma kinase (ALK) rearrangement, ROS1 rearrangement, and programmed death-ligand 1 (PD-L1) expression." (PMID 30443294, 2018).
lung adenocarcinoma (continued). "Two of these mutations affect the same allele of the Cfh gene, mutated in 340 of 20,238 cases in the COSMIC database among which many lung adenocarcinoma and lung squamous cell carcinomas, a disease with a known role for ALK as a tumor driver in a subset of cases." (PMID 29492199, 2018). "Lung adenocarcinomas harboring oncogenic driver mutations at the level of EGFR and ROS1 and ALK rearrangements have a lower mutational load, often occur in never smokers and are sensitive to targeting with specific inhibitors and this offered new therapeutic perspectives for these patients." (PMID 30060526, 2018). "In order to define the optimum primary antibody incubation time for ALK, serial sections of lung adenocarcinomas were incubated with anti-human ALK antibody clone 5A4 for 2, 4, 8, 16, or 32 min, while the incubation time of the secondary antibody was kept constant at 8 min." (PMID 30326973, 2018). "Patients with lung adenocarcinoma whose tumor harbor specific gene mutations, such as epidermal growth factor receptor (EGFR) mutation or anaplastic lymphoma kinase (ALK) fusion, derive significant benefit from targeted agents, tyrosine kinase inhibitors (TKIs), and have better prognosis." (PMID 30509312, 2018). "Interestingly, lung adenocarcinomas associated with specific driver mutations, such as EGFR, ALK or ROS1 display a specific pattern of CpGs methylation." (PMID 30060526, 2018). "Lung adenocarcinoma with ALK arrangement was diagnosed based on clinical and pathological findings." (PMID 30257437, 2018). "Alternatively, detecting the presence of the echinoderm microtubule-associated protein-like 4 (EML4)-anaplastic lymphoma kinase (ALK) fusion gene, termed the ALK-rearrangement, is routinely performed in lung adenocarcinomas and allows the treatment of such patients with anti-ALK targeted therapy." (PMID 28432274, 2017). "The aim of this study was therefore to evaluate the occurrence of DVT/VTE in patients with EGFR- and ALK-mutated forms of lung adenocarcinoma compared with non-mutated cases." (PMID 28560038, 2017). "The finding of ALK/EGFR coaltered lung adenocarcinoma cases may be explained by clonal evolutionary dynamics and the resulting complex clonal architecture of lung adenocarcinoma samples." (PMID 28887531, 2017). "Therefore, ALK gene translocation can be measured reliably in material from either primary or metastatic tumours in lung adenocarcinoma patients." (PMID 28887531, 2017). "One thousand thirteen patients with lung adenocarcinoma underwent a mutational analysis test during the study period at the Karolinska University Hospital; among them, 104 (10.3%) tested positive for a EGFR mutation, 52 (5.1%) had an ALK translocation." (PMID 28560038, 2017). "Forty-two (7.9%) of the 534 lung adenocarcinoma patients were ALK IHC-positive." (PMID 29156778, 2017). "To address these questions, we conducted a comprehensive study in a large cohort of Chinese patients with lung adenocarcinoma and determined the associations between 5 common driver genes (EGFR, KRAS, ALK, RET, BRAF) and pathological subtypes, as well as their combined impact on prognosis." (PMID 29137260, 2017). "Frequent decrease of FSTL1 expression in adenocarcinoma with KRAS mutation or ALK fusion and in smokers implies that FSTL1 has a critical role and may be a potential therapeutic target for some specific molecular types of lung adenocarcinoma." (PMID 28852126, 2017). "We tested these hypotheses further by developing our own in vitro models of crizotinib resistance using human ALK+ lung adenocarcinoma cells, studying both the effects of IGF-1R inhibition shortly after crizotinib treatment and chronic crizotinib exposure." (PMID 29066738, 2017). "ALK rearrangements in NSCLC were first described in lung adenocarcinomas." (PMID 27386342, 2016). "A total of 52 patients with ALK-rearranged lung adenocarcinoma were enrolled." (PMID 27756333, 2016).
lung adenocarcinoma (continued). "Whether EGFR tyrosine kinase inhibitors or ALK inhibitors are still effective for these special lung adenocarcinomas with clear cell component like lung adenocarcinoma is uncertain and calls for further investigation." (PMID 27013585, 2016). "We report the re-biopsied diagnosis of a patient with anaplastic lymphoma receptor tyrosine kinase (ALK)-positive lung adenocarcinoma successfully treated with ceritinib 450 mg/day taken with food following disease progression and gastrointestinal intolerance to crizotinib." (PMID 27480287, 2016). "Recurrent mutations in CDH10 have recently been reported in EGFR/KRAS/ALK mutation-negative lung adenocarcinoma in never-smokers and as a prognostic mutation signature in colorectal cancer." (PMID 27093186, 2016). "Thus, there was a significant PFS benefit of first‐line crizotinib versus first‐line standard chemotherapy in Chinese patients with ALK‐positive lung adenocarcinoma." (PMID 26880708, 2016). "Similarly, National Comprehensive Cancer Network (NCCN) and European Society for Medical Oncology (ESMO) recommend all patients with lung adenocarcinoma to be tested for ALK rearrangements, among other genetic alterations." (PMID 26838801, 2016). "This study also indicated that crizotinib has promising efficacy in ALK‐positive Chinese lung adenocarcinoma patients who received it as a second‐line treatment after PD had occurred on first‐line chemotherapy, with a median PFS of about 10 months and an ORR of more than 60% in these patients." (PMID 26880708, 2016). "EGFR, KRAS, and ALK alterations are the major genetic changes in lung adenocarcinoma." (PMID 26992209, 2016). "We presented the results of the EGFR, KRAS and ALK mutational analyses in patients with lung adenocarcinomas in a prospective study, regardless of clinical stage." (PMID 27655296, 2016). "In patients with lung adenocarcinoma, hypothesis-generating studies have strongly suggested that ALK status could be determined based on testing of CTCs, with comparable results as testing of tumor tissues." (PMID 26993609, 2016). "To further address this issue, we collected data on 6 patients with lung adenocarcinomas who were Ventana IHC ALK(D5F3)-positive and FISH-negative from 3 hospitals in Beijing, and assessed these patients clinically following the administration of crizotinib therapy." (PMID 27418132, 2016). "This suggests that ALK‐positive lung adenocarcinoma patients who are assessed as having PD on first‐line chemotherapy might continue to receive and benefit from crizotinib." (PMID 26880708, 2016). "Rearrangements in the ALK gene are found in 5%–7% of lung adenocarcinomas." (PMID 26371045, 2015). "Therefore, screening for the EGFR and KRAS mutations, and ALK and KIF5B-RET translocations should be considered during initial diagnosis of lung adenocarcinomas." (PMID 26268359, 2015). "In this study, we evaluated the status of driver gene mutations in lung adenocarcinoma samples from 198 East Asian female never-smokers using the MassARRAY® LungCarta Panel and ALK, ROS1, and RET fusion assays." (PMID 25760072, 2015). "Additionally, translocations involving the anaplastic lymphoma kinase (ALK) are found in 7 % of adenocarcinomas of the lung and can be targeted by several ALK TKIs (crizotinib and ceritinib)." (PMID 26668062, 2015). "Interestingly, most of these strongly staining RTKs were mutually exclusive, evoking the oncogenic driver mutations (EGFR, KRAS, ALK, and ROS1) observed in lung adenocarcinoma." (PMID 25989941, 2015). "A total of 1356 lung adenocarcinoma cases from April 2007 to May 2013 were sequenced for EGFR kinase domain mutations, KRAS mutations, HER2 kinase domain mutations, BRAF mutations, ALK fusions, ROS1 fusions, RET fusions and AKT1 mutations." (PMID 26486077, 2015).
lung adenocarcinoma (continued). "Taken together, our data suggest one-step screening platform for KIF5B-RET as well as EGFR, K-RAS, ALK oncogenic mutations be necessary for lung adenocarcinoma patients because EGFR or KRAS mutation are not infrequently found in KIF5B-RET-positive patients." (PMID 26268359, 2015). "We report a case of 50-year-old Japanese female with anaplastic lymphoma kinase (ALK)-positive, crizotinib-resistant lung adenocarcinoma, whose leptomeningeal carcinomatosis and spinal cord metastases were dramatically improved by the second-generation ALK inhibitor alectinib." (PMID 31149429, 2015). "However, the cumulative data for lung adenocarcinoma, breast and liver cancers contain a few hundred different mutations in ALK, but few in its sister LTK, an imbalance that is inconsistent with ALK being an activated driver in these cancers." (PMID 24806839, 2014). "Some studies from France and Korea demonstrated that clone 5A4 could accurately identify ALK rearranged lung adenocarcinoma as compared with FISH." (PMID 24667320, 2014). "In NSCLC patients of East Asian descent, lung adenocarcinomas had a markedly higher rate of ALK rearrangements than squamous cell carcinomas, while this was not the case in Caucasians, likely due to more cases of squamous cell carcinoma in Caucasians than East Asians (2.1% versus 0.8%)." (PMID 24959902, 2014). "We analyzed 410 unselected lung adenocarcinomas by ALK IHC (D5F3 clone) and FISH." (PMID 24667320, 2014). "Similar to the ALK-positive lung adenocarcinomas in an early stage 4, these features might suggest that they have a more invasive nature than those with more GGO components." (PMID 24403104, 2014). "The somatic mutation profile in lung adenocarcinomas lacking targetable EGFR or KRAS mutations or ALK rearrangements in never-smokers is highly complex." (PMID 24576404, 2014). "So far, no reports have evaluated the association between ALK rearrangement status and imaging findings in advanced-stage lung adenocarcinoma." (PMID 24403104, 2014). "Notably, the vast majority of ALK gene rearrangements were observed in lung adenocarcinoma specimens." (PMID 25527865, 2014). "To evaluate the potential role of IHC (primary antibody CST D5F3 coupled with secondary DAKO Envision system) as a detection or screening method for ALK, we analyzed a unselected cohort of 368 lung adenocarcinoma cases retrospectively compared the IHC results with FISH in this study." (PMID 24667320, 2014). "We identified novel somatic mutations in EGFR/KRAS/ALK-negative lung adenocarcinoma in never-smokers and investigated the mutation frequency of altered genes." (PMID 24576404, 2014). "Many other RTKs are known to play a role in lung adenocarcinoma, including ALK and ERBB2, and it is interesting to speculate that DOK2 may also inhibit lung tumorigenesis driven by those oncogenes." (PMID 24255704, 2013). "For lung adenocarcinomas, epidermal growth factor receptor (EGFR) tyrosine kinase inhibitors have been approved for treatment of tumors carrying EGFR gene mutations, and crizotinib for tumors with anaplastic lymphoma kinase (ALK) gene rearrangements." (PMID 24236184, 2013). "The goal was to analyse the clinicopathological features of ALK-rearranged lung adenocarcinomas." (PMID 23922677, 2013). "Eighty ALK-rearranged and 213 ALK-negative (91 epidermal growth factor receptor-mutated; 29 K-ras-mutated; 93 triple-negative) resected lung adenocarcinomas were analyzed for several histomorphological parameters and histological subtype." (PMID 24194854, 2013). "In our study, 572 lung adenocarcinomas were divided into ALK-rearranged, common driver mutation, and pan-negative groups according to mutational status." (PMID 23922677, 2013). "In addition to the EML4-ALK fusion, not only other fusion partner for ALK gene, but also novel kinase gene fusions have been discovered in a subset of lung adenocarcinoma." (PMID 23617234, 2013).
lung adenocarcinoma (continued). "This leads to consider the need for studies that enhance the molecular changes that, like EGFR, K-ras and ALK genes for lung adenocarcinoma, at prognostic and/or predictive levels may give chances for an effective therapeutic response in these patients." (PMID 23236352, 2012). "KLC1-ALK may be rare but exists in lung adenocarcinoma, and the patients with this fusion are highly likely to benefit from ALK inhibitor therapy as do patients with other ALK fusions." (PMID 22347464, 2012). "The interphase in situ hybridization technique is becoming a routinely available standard molecular assessment requested to reference Pathology Labs, due i.e. to the value of the Her-2 gene in breast, gastric cancers, 1p/19q in oligodendrogliomas or EGFR and ALK genes in lung adenocarcinoma." (PMID 23236352, 2012). "Since that time, additional ALK fusion partners have been identified and transforming versions of ALK as well as aberrant ALK expression have been shown in cancers other than lymphoma including adenocarcinomas of the lung, neuroblastomas, breast and esophageal cancers." (PMID 22347506, 2012). "Furthermore, an individualized model that combines the rad-score and clinico-radiological data may aid in the management of patients with advanced ALK-positive lung adenocarcinoma." (PMID 40606995, 2025). "In addition, four lung adenocarcinoma RDAA+ patients received crizotinib therapy (another ALK inhibitor, 250–500 mg /day for 4 weeks), three out of four patients achieved objective response: one complete response (CR, patient #01) and two partial response (PR, patients #02 and #04)." (PMID 40246819, 2025). "Moreover, the research have indicated that patients with ALK rearrangements are particularly susceptible to developing brain metastases, with an incidence as high as 66% in ALK-positive (ALK+) patients, whereas the overall incidence in all lung adenocarcinoma cases is lower." (PMID 40606995, 2025). "Additionally, lung adenocarcinomas with calcification may be associated with ROS1 fusions as well as EGFR mutations and ALK fusions." (PMID 39391406, 2024). "Besides contrasting these findings using publicly available data, in this study we hypothesized that ROS1+ NSCLC is defined by specific transcriptomic signatures compared to other oncogene-driven tumors like ALK+ or RET+ lung adenocarcinomas." (PMID 39737401, 2024). "By focusing on EGFR/ALK wild‐type patients, we aimed to elucidate molecular mechanisms and potential biomarkers related to PD‐L1 expression and the response to immunotherapy within this specific and clinically significant subgroup of lung adenocarcinoma patients." (PMID 38396367, 2024). "Furthermore, in the context of H3122 lung adenocarcinoma, research findings suggested that the combination of ALK inhibition with a PI3K inhibitor (ZSTK474) or anticoccidial agent (salinomycin) reversed stem-like cell characteristics and impeded the development of acquired resistance." (PMID 38397899, 2024). "Therefore, our research focuses on patients with EGFR/ALK wild‐type lung adenocarcinoma who may benefit from ICI treatment." (PMID 38396367, 2024). "Thus, this study aimed to explore the epidemiology, clinical characteristics, and OS of treatment-naïve ALK-positive advanced lung adenocarcinoma patients, focusing on smoking status and ALK-TKIs treatment, using a nationwide cancer registry database in Taiwan." (PMID 37007097, 2023). "In this review, it was found that 66.7% of cases with immunotherapy-induced histological transformation were classified as lung squamous cell carcinoma (LSCC), while histological conversion into lung adenocarcinoma (LUAD) without EGFR or ALK gene mutations has rarely been reported." (PMID 38022621, 2023).